VHL (von Hippel-Lindau tumor suppressor)
Diseases named in the same sentence as VHL in open-access papers (continued):
Sharing a sentence is not in itself a finding about the gene and the disease.
cancer (continued). "Another option is the HIF2 inhibitor belzutifan, already approved for cancer treatment in patients with mutations in VHL, an E3 ubiquitin ligase essential for HIF ubiquitination and degradation." (PMID 38652538, 2024). "In these cancers, mutations or deletions in the VHL gene result in a loss of function, preventing the degradation of HIF-α subunits under normoxia." (PMID 39858553, 2024). "Individuals carrying a disease-causing germline variant in the VHL gene face the risk of developing both benign and malignant tumors across multiple organs." (PMID 39201746, 2024). "The most important initial component is the identification of accurate, precise markers for a specific cancer type, such as VHL-associated ccRCC." (PMID 39062684, 2024). "HIF-1α protein was detected in VHL-deficient renal epithelial cells, and also ccRCC, suggesting its implications in cancer progression." (PMID 37176098, 2023). "In this respect, it is interesting to note that ubiquitin ligases that modulate AurkA stability, for example, Fbxw7 and VHL, are frequently mutated in cancer (references 22, 50 and references therein)." (PMID 36797043, 2023). "One feature of ccRCC that distinguishes it from other cancer types is that ccRCC is typified by inactivating mutations in the VHL gene (reviewed in 24), whereas other cancers within the TCGA PanCan dataset have more heterogeneous etiologies." (PMID 37745397, 2023). "For clarity, we initially describe cancers occurring in the VHL syndrome and, then, sporadic cancers with mutations in VHL, HIF, and PHD genes." (PMID 37477829, 2023). "We subsequently explored the association of PGAM1 mutations with common cancer progression genes, such as VHL, PBRM1, and SETD2." (PMID 37847178, 2023). "VHL disease is a cancer syndrome which is inherited in a dominant manner and its development predisposes to a number of other cancers linked to mutations in the VHL gene." (PMID 36036061, 2023). "Currently, several HIF-2α inhibitors are also being tested in clinical trials, and HIF-2α inhibitor belzutifan was approved for use in VHL-associated cancers." (PMID 36846589, 2023). "Clear cell RCC (ccRCC) represents about 75% of all RCC cases, is the most aggressive form of this cancer type, and is known to be closely related with mutation of the von Hippel-Lindau gene (VHL)." (PMID 38115281, 2023). "The most frequent mutations in a large panel of 1123 cancer-related genes in the overall population of RCC patients were VHL (51%), PBRM1 (35%), BAP1 (16%), KMT2D (15%), PTPRD (15%), and SETD2 (15%)." (PMID 37427096, 2023). "Mutation, silencing, deletion or methylation of VHL contributes to tumorigenesis and cancer progression." (PMID 36813772, 2023). "The Von Hippel–Lindau (VHL) tumor suppressor gene has been implicated in tumorigenesis of various types of carcinoma and linked with their aggressive biological behavior." (PMID 36036061, 2023). "Loss of VHL, which causes oxygen‐independent stabilization of HIF1α, is reported to increase the predisposition to some cancers." (PMID 34779571, 2022). "In this study, we assessed the current perspectives on belzutifan for the management of VHL-associated tumors among experts at designated VHL and cancer centers." (PMID 36310638, 2022). "Functional impairment of the von Hippel–Lindau tumor suppressor (pVHL) is causative of a familiar increased risk of developing cancer." (PMID 35205757, 2022). "The CIViC knowledgebase is also completely open‐access and user‐friendly, making it a unique resource for VHL patients, families and community groups who can freely access information on variants and cancer‐types of interest." (PMID 35475554, 2022). "Non-cancerous VHLR200W Chuvash polycythaemia mutation was normal with regard to TFAM regulation in contrast to all other VHL syndromic cancer mutations, which suggests that impaired mitochondrial biogenesis is an important feature of the VHL syndrome." (PMID 35760869, 2022).
cancer (continued). "Re-examination of the NGS data from the proband’s initial hereditary cancer testing identified the T allele at c.593 in the VHL gene in ~6% of the sequencing reads (77 reads of the total 1298 at this base pair position)." (PMID 35304467, 2022). "RCC was distinguished from other cancers by a somatic mutation of the VHL gene which occurred frequently, in most RCC especially clear cell subtype (ccRCC)." (PMID 36542612, 2022). "Patients with a personal history of cancer with known germline VHL variants with non-syndromic VHL phenotypes and/or phenotypes discordant with genotype were selected for germline evaluation." (PMID 35774415, 2022). "Von Hippel-Lindau (VHL) disease is an autosomal dominant genetic neoplastic disorder caused by germline mutation or deletion of the VHL gene, characterized by the tendency to develop multisystem benign or malignant tumors." (PMID 35505422, 2022). "In summary, our findings uncover a previously unidentified role of ZMYND8 in regulating PRC2 activities and promoting a Polycomb-dependent to -independent switch of EZH2 functions in hypoxia-exposed or VHL-deficient cancer cells." (PMID 33593912, 2021). "Mutations of HIF regulators–such as VHL, even in the form of germline ones (von-Hippel Lindau syndrome)–are much more frequent in cancers." (PMID 34257622, 2021). "VHL can inhibit the transcriptional function of HIF1α to glucose metabolism associated genes in various cancers especially renal cancer." (PMID 35006464, 2021). "Murine ccRCC models and human ccRCC cancers feature mTOR activation and cellular overgrowth after loss of VHL and PBRM1 gene function." (PMID 33920158, 2021). "Expression in ccRCC primary cancers and metastatic tissues associated with the p-VHL content, transcriptional, and growth factors expression." (PMID 34563045, 2021). "Accordingly, the genetic prototype of HIF-deregulated cancer is the sporadic renal cell carcinoma, where the incidence of the loss of function mutation of VHL is 50%, resulting in an angiogenesis-dependent tumor." (PMID 34257622, 2021). "A recent phase II trial with the HIF-2 alpha inhibitor belzutifan (MK-6482) demonstrated promising efficacy and tolerability in patients with VHL-mutated cancers, including RCC, and the drug has recently been approved by the FDA for this indication." (PMID 35054417, 2021). "In subsequent studies, it would be essential to test the involvement of Smurf2 in HIF-1α regulation in various cancer types especially including both VHL-sufficient and VHL-deficient cancers." (PMID 34611473, 2021). "Exaggerated VEGF signaling caused by pVHL loss is consistent with the hyper-angiogenic phenotype of cancers arising in VHL individuals." (PMID 34680266, 2021). "miRNAs and hosts were less co-expressed in KIRC than other cancer types, possibly due to its frequent VHL mutations." (PMID 34572448, 2021). "As hypoxia has been reported to trigger epithelial-to-mesenchymal transition (EMT) in several types of cancer, we investigated the potential of the pseudo-hypoxic state induced by VHL-R167Q to modulate EMT-associated markers." (PMID 34359798, 2021). "This study aimed to investigate PD-1, PD-L1, and PD-L2 expression in ccRCC primary cancers and metastatic tissues associated with the p-VHL content, transcriptional, and growth factors expression." (PMID 34563045, 2021). "Tissue specificity in cancer is best evidenced by hereditary cancer predisposition syndromes in which the underlying gene defects, such as mutations in APC, BRCA1, and VHL, are associated with a high risk of developing tissue-specific cancer types." (PMID 34440884, 2021).
cancer (continued). "RCC is considered to be cancer derived from metabolic changes owing to the high frequency of mutations in genes that control aspects of metabolism, such as mutations in VHL and MET." (PMID 34620162, 2021). "In fact, PT2385 has entered its phase II clinical trial (NCT03108066) evaluating its efficacy in patients with advanced cancers carrying a VHL germline mutation." (PMID 33329393, 2020). "The VHL gene showed slightly higher evolutionary variations compared with other cancer risk regions." (PMID 32731489, 2020). "Other studies have found that specific mutations at the Y98 position will cause different VHL cancer phenotypes with Y98H causing type 2B disease and Y98N causing type 2A disease by modulating the efficacy of binding to HIFα." (PMID 33151962, 2020). "Germline VHL gene mutations predispose affected subjects to the development of benign and malignant tumors located at the central nervous system and visceral organs." (PMID 32751108, 2020). "After the VHL mutations were first described in an ophthalmic disease, multiple studies subsequently confirmed that VHL mutations can cause a variety of diseases including cancers." (PMID 33329393, 2020). "STF-31 binds directly to Glut1 and interferes with glucose uptake, causing necrosis in VHL-deficient cancer cells." (PMID 33053779, 2020). "This particular compound was identified to have potent cytotoxic effects in VHL-deficient cancer cells, but very little efficacy in wild-type (WT) VHL cells." (PMID 32392870, 2020). "We then identified the potential tumour suppressor genes regulated by HIF‐1/2α in VHL‐deficient ccRCC cancer cells by subtractive proteomics strategy." (PMID 32537867, 2020). "Mutations in VHL related to formation of the E3 ubiquitin ligase complex lead to von Hippel–Lindau syndrome, which can exhibit both ciliopathy and cancer phenotypes." (PMID 32825105, 2020). "STF-62247 is believed to induce autophagy in cancer cells, as treatment produces large, cytoplasmic vacuoles in both WT-VHL and VHL-deficient cells." (PMID 32392870, 2020). "With respect of newly defined entities, we found VHL mutations in 1 of 2 multilocular cystic renal cell neoplasias of low malignant potential and in 1 of 4 Xp11.2 translocation carcinomas." (PMID 32076485, 2020). "VHL is mutated or silenced in >50% cases of sporadic clear cell renal cell carcinomas (ccRCC), and autophagy is observed in most cancer cells." (PMID 30902965, 2019). "These degraders have therefore been successfully used in the degradation of several cancer and neurodegenerative associated proteins, with arguably more variation compared to cereblon- or VHL-recruiting PROTACs." (PMID 31500395, 2019). "By looking at the VHL interactors involved, it is therefore possible to identify other candidate genes for mutations leading to very similar cancer types." (PMID 30943211, 2019). "STF-31 binds directly to the Glut1 transporter, blocking glucose uptake, resulting in necrosis in VHL-deficient cancer cells." (PMID 31597342, 2019). "Different cancer types appear to be caused by mutations changing the surface of specific parts of the VHL protein." (PMID 30943211, 2019). "In particular, our simulation of phosphorylation events impaired by cancer-related mutations shows that correct interpretation of VHL fate benefits from the integration of different information sources." (PMID 30943211, 2019). "Extensive curation from certain groups (eg, the University Health Network curation of VHL variants) disproportionately increases representation for certain genes, cancers, and variant types." (PMID 31618044, 2019). "SNIPERs have therefore been used to degrade several cancer-associated proteins and with similar potency to VHL-recruiting PROTACs (DC50 nM range)." (PMID 31500395, 2019).
cancer (continued). "This article describes a large-scale analysis to relate known VHL mutations to specific cancer pathways by looking at the molecular interactions." (PMID 30943211, 2019). "While HIF and HIF-dependent signaling remain to be therapeutically interrogated in cancers with VHL loss, during the past few years, there have been several emerging studies that studied the role of VHL in the regulation of HIF-independent pathways." (PMID 29562667, 2018). "To compare inherited with sporadic cases, we reanalyzed these data using our pipelines to establish how the wild-type VHL allele was lost in these cancers." (PMID 29656891, 2018). "It is this population size that best explains the pronounced differences in penetrance and age of incidence between somatic and inherited cancers, given a VHL driver mutation rate of ∼2 per million cells per year." (PMID 29656891, 2018). "Of great interest, we sequenced VHL genes from 44 cases of ccRCC cancer tissues, and found that 13 cases of them carried VHL mutations, among which 8 cases were missense mutations with no E3 ligase activities." (PMID 28643803, 2017). "Reductive carboxylation is associated with hypoxia in cancer cells and the loss of VHL is associated with the hypoxic-like response and the metabolic pathways are rewired accordingly." (PMID 28806730, 2017). "While dysregulated HIF1α and pAkt are associated with most forms of cancer, mutations in VHL are found predominately in ccRCC." (PMID 29053101, 2017). "The von Hippel-Lindau (VHL) tumor suppressor gene is lost or mutated in 60–90% in sporadic cases and is a major contributor to development of this cancer." (PMID 28859644, 2017). "Further experiments found that in several different types of cancer, higher levels of Daam2 are linked with the presence of lower levels of VHL." (PMID 29053101, 2017). "Analysis of human cancer data, along with our functional studies in mouse models, strongly suggests that Daam2 expression results in the loss of VHL protein." (PMID 29053101, 2017). "At least in the setting of VHL-associated cancer, we consider that there is persuasive evidence for pro- and anti-tumourigenic actions of different components of the HIF pathway." (PMID 28315322, 2017). "In hereditary VHL disease, mutations and loss of heterozygosity (LOH) at the VHL locus in the cancer cells inactivates VHL and results in a constitutively high level of HIFα even in the presence of oxygen." (PMID 27222660, 2016). "Inactivation of pVHL is the underlying driver of VHL-related cancer, including inherited VHL disease and sporadic ccRCC." (PMID 27517496, 2016). "In another study, miR-28-5p was defined as a critical regulator of Mad2 translation and the function of the mitotic checkpoint in VHL-associated cancers." (PMID 27729617, 2016). "KIRC has been reported to have a high frequency of Von Hippel-Lindau (VHL) mutation and show distinct exclusivity from other 11 cancer types." (PMID 26148869, 2015). "mRNA levels of both PAG1 and the well-known hypoxia-inducible CAIX were robustly upregulated by 3- to 11-fold in all cancer cell lines examined, except in VHL-deficient 786–0 ccRCC in which PAG1 levels were constitutively high." (PMID 26007655, 2015). "Our pan-cancer regression tree shows that VHL mutations correlate with significant reductions in average levels of CGI methylation in KIRC tumors." (PMID 25960768, 2015). "More recently, Niu and colleagues provided the first in vivo evidence that KDM5C serves as a tumor suppressor following VHL loss in ccRCC and that cancer-specific mutations were inactivating." (PMID 24622842, 2014).
cancer (continued). "Of these, VHL was mutated in 5 samples with an allele fraction ranging from 18-21% and cancer cell fraction from 76-100%, suggesting a clonal somatic mutation carried by the subpopulation of neoplastic “stromal” cells." (PMID 25589003, 2014). "Given the key role of HIFs in this pathway, we analyzed ccRCCs because VHL loss-of-function is common and represents an O2-independent mechanism to activate HIFs in cancer cells." (PMID 25326682, 2014). "We first examined the mutation status of the VHL gene in 241PCC tumors from the Catalogue of Somatic Mutations in Cancer (COSMIC)." (PMID 25298778, 2014). "Hallmarks of this cancer include a highly hypoxic and glycolytic nature and an increased dependency on glucose, all characteristics associated with VHL loss and HIF stabilization which play a central role in the pathogenesis of RCC." (PMID 23958461, 2013). "VHL syndrome is an inherited disorder caused by germline point mutations in the VHL gene and is characterized by a predisposition to a variety of benign and malignant tumours." (PMID 23785518, 2013). "Generally, a loss of VHL expression in cancer leads to up-regulation of HIF-1α and increased VEGF expression." (PMID 22390300, 2012). "There are characteristic abnormalities of the VHL gene in germline mutations from VHL disease and somatic mutations from sporadic cancers: more than a half of the former are missense mutations whereas 70% of the latter are frameshift mutations." (PMID 22462637, 2012). "It is possible that the single hit allelic loss of the VHL gene increased the risk of cancer development." (PMID 22462637, 2012). "HLRCC-associatedkidney cancer is markedly different from kidney cancer associated with otherhereditary cancer syndromes, such as VHL, HPRC, and BHD." (PMID 18695737, 2008). "However, pVHL is frequently downregulated in numerous cancers harboring wild-type VHL, and underlying mechanisms remains elusive." (PMID 41015595, 2025). "Additionally, the inactivation of tumour suppressor genes such as VHL has been implicated in cancer progression." (PMID 40673609, 2025). "Von Hippel-Lindau (VHL) disease is an autosomal dominant disorder caused by germline pathogenic variants of the VHL gene, which can lead to abnormal growth of blood vessels and cause the development of benign or malignant tumors, as well as cysts in diverse organs." (PMID 40213016, 2025). "Mutations in VHL are among the most frequently observed in ccRCC, and it has been established that the suppression, removal, or methylation of VHL promotes tumorigenesis and cancer progression." (PMID 37762031, 2023). "As a result, HIF1α may promote miR-183/96/182 cluster expression, out of which miR-183 can also target VHL mRNAs to further inhibit its expression and constitutively promote HIF1α expression and associated cancer progression in a feedback loop mechanism." (PMID 37583933, 2023). "Suppression of exosomal miR-204 secretion or blocking regulation between miR-204/VHL axis in adipose tissue might hold promise for fighting cancer-associated cachexia and improving patient survival." (PMID 37620316, 2023). "SETDB1 accumulation may underlie a molecular mechanism for VHL inactivation involved in cancer progression." (PMID 37850636, 2023). "In addition, as a highly frequently mutated gene in ccRCC, VHL has been confirmed as the key indicator for evaluating cancer metastasis and therapeutic efficacy." (PMID 36171882, 2022). "Therefore, our findings raise concerns about the potential toxicities in bone growth associated with cancer therapies targeting Bcl-xL with VHL-based PROTACs in children." (PMID 36438482, 2022). "Notably, we observed that ZMYND8 antagonizes Polycomb-dependent function to inhibit H3K27me3 level only in hypoxia- or VHL-deficient cancer cells, conditions of which are commonly associated with the up-regulation of HIF transcription factors." (PMID 33593912, 2021).